UBC (ubiquitin C)
Diseases named in the same sentence as UBC in open-access papers (continued):
Sharing a sentence is not in itself a finding about the gene and the disease.
colon carcinoma (4 papers, 2011 to 2024). "Among the identified proteins, ATPase subunit beta-1 is unique in that it may interact with calgranulin B to facilitate colon cancer progression and/or communicate directly with polyubiquitin-C." (PMID 28152021, 2017). "In particular, UBC, MCM2, and COPS5 show stronger dependencies in colon cancer comparing with the mean across all cell lines (six sigma or greater dependency)." (PMID 30723737, 2019).
colorectal cancer (4 papers, 2012 to 2020). A primary or metastatic malignant neoplasm that affects the colon or rectum. "Ubiquitin C is a small regulatory protein that labels proteins to be transported and destroyed in proteasomes, and its role in colorectal carcinogenesis and colorectal cancer prognosis was recently reviewed." (PMID 24324931, 2013).
hepatocellular carcinoma (4 papers, 2012 to 2021). A malignant tumor that arises from hepatocytes. "PRKDC, PARP1, NPM1 and XRCC6 are hepatocellular carcinoma over-expression genes which modulate cell cycle regulation network through the modulation of UBC." (PMID 24564241, 2013).
leukemia (4 papers, 2016 to 2026). A malignant (clonal) hematologic disorder, involving hematopoietic stem cells and characterized by the presence of primitive or atypical myeloid or lymphoid cells in the bone marrow and the blood. "In conclusion, Cas9-mediated chromosomal translocations of the KMT2A gene in UBC HSPCs represent novel tool for studying pre-leukemia development and probably also leukemia onset ex vivo." (PMID 41145673, 2026). "To test the effect of acute Midn deletion on Eμ-Myc driven leukemia, we transplanted bone marrow from Eμ-Myc transgenic or non-transgenic UBC-Cre-ERT2;Midnfl/fl mice (CD45.2) to lethally irradiated WT recipients (CD45.1)." (PMID 38625151, 2024). "To further demonstrate the in vivo therapeutic potentials of targeting Prmt1 in the clinically relevant setting, we transplanted MOZ-TIF2 leukemia cells carrying UbC-luciferase reporter without any pretreatment into syngeneic mice and then subjected them to AMI-408 treatment." (PMID 26766589, 2016).
Alzheimer disease (3 papers, 2015 to 2021). A progressive, neurodegenerative disease characterized by loss of function and death of nerve cells in several areas of the brain leading to loss of cognitive function such as memory and language. "A recent study reportedYWHAZ, UBC and SDHA (alongsideHMBS) to be a suitable reference gene panel for use in human brain from both normal control patients and patients with Alzheimer’s disease (Coulsonet al., 2008)." (PMID 37942409, 2021).
Hypertension (3 papers, 2013 to 2019). The presence of chronic increased pressure in the systemic arterial system. "The common area between the hypertension only- and hypercholesterolemia plus sham groups showed up-regulated focus genes related to UBC, APP, SERPINB2, TNF and HNF4A, and down-regulated focus genes related to UBC." (PMID 23874591, 2013). "According to the inference, genistein binds to the FGF1 protein in fibroblasts of the skin; the FGF1 protein activates the FGFR1 protein in the muscle cells of the heart; FGFR1 protein activates the UBC protein; the UBC protein activates the CTGF protein, and CTGF affects hypertension." (PMID 31138123, 2019). "The network in the MCA with the largest number of down-regulated focus genes affected by hypertension was related to MAPK, ERK 1/2, Akt, 26s proteasome, histone and PKC, while the network with the second largest number of down-regulated focus genes was related to UBC." (PMID 23874591, 2013).
liver cancer (3 papers, 2008 to 2024). An epithelial or non-epithelial malignant neoplasm that arises from the liver. "The interacting protein carbamyl phosphate synthetase 1 (CPS1) has been shown to be downregulated in both HCC and AFB1 exposure, highlighting the importance of studying the mechanisms underlying UBC upregulation in liver cancer and its interaction with CPS1." (PMID 38201191, 2024). "In hepatic cancer cell lines, the first six stable reference genes were YWHAZ, ACTB, B2M, UBC, HPRT1, and RNA18S." (PMID 34752497, 2021). "In hepatic cancer cell lines, B2M, GAPDH, UBC, and HPRT1 were the first four stable nominees, respectively, and RNA18S was determined as the least stable ones." (PMID 34752497, 2021). "Besides that, a panel of five nominees, including ACTB, HPRT1, UBC, YWHAZ, and B2M showed higher stability than others in hepatic cancer cell lines." (PMID 34752497, 2021). "Moreover, in hepatic cancer cell lines including Huh7, HepG2, and PLC-PRF5, ACTB, HPRT1, UBC, B2M, and YWHAZ were among the first six stable genes ranked by geNorm, NormFinder, and RefFinder algorithm." (PMID 34752497, 2021). "Similarly, a panel of five reference genes, namely ACTB, HPRT1, UBC, YWHAZ, and B2M is also recommended for RT-qPCR data normalization of three hepatic cancer cell lines, including Huh7, HepG2, and PLC-PRF5." (PMID 34752497, 2021).
major depression (3 papers, 2011 to 2019). "A recent bioinformatics paper has identified ubiquitin c as a possible “switchboard” gene for psychiatric disorders including depression." (PMID 24040027, 2013). "For example, the ubiquitous protein, UBC, was abnormally expressed in schizophrenia samples and interacted with the maker genes of schizophrenia (i.e. TSC2, SCNN1A and USP2), bipolar disorder (i.e. MUSK), and major depression (i.e. MUSK and FLT3)." (PMID 22373040, 2011). "These genes included SBNO2, CEACAM5, AKAP1, UBC, ACTB, UBB, and FOS for schizophrenia; SEC24C, PGLYRP1, ARHGAP4, RPL22, SLC6A11, and SYK for bipolar disorder; and SRRT, PARK2, LILRA4, STK17A, IGFBP2, and NF1 for major depression." (PMID 22373040, 2011).
schizophrenia (3 papers, 2011 to 2022). A major psychotic disorder characterized by abnormalities in the perception or expression of reality. "Our findings suggest that a combination of MLR, MPV, PLR, and UBC could be used to predict acute stage of schizophrenia." (PMID 35463529, 2022). "The top ranked genes in centrality analysis, UBC, ACTB, and UBB, were all abnormally expressed in schizophrenia samples." (PMID 22373040, 2011).
viral infection (3 papers, 2015 to 2020). "To evaluate the role of TNIK in CD8+ T cells during an acute viral infection in vivo, we generated a tamoxifen inducible TnikF/F;UBC-Cre+ mouse." (PMID 32242021, 2020). "As expected, in comparison with single reference gene, the normalization of OsPR1b using UBQ 10 + GAPDH and UBC + Actin1, respectively, resulted in significant increase in transcript levels under virus infection conditions." (PMID 26497487, 2015).
anemia (2 papers, 2011 to 2012). A reduction in the number of red blood cells, the amount of hemoglobin, and/or the volume of packed red blood cells. "Furthermore, a follow up of Vhlfloxed-UBC-Cre-ERT2 mice revealed that they started to show anemia after a longer time period upon Vhl gene inactivation (hematocrit %: 42.62±2.22 in Vhlfloxed versus 33.2±3.8 in Vhlfloxed-UBC-Cre-ERT2; n = 7, p = 0.041)." (PMID 21811636, 2011).
atopic eczema (2 papers, 2015 to 2022). A common chronic pruritic inflammatory skin disease with a strong genetic component. "It seems that a decreased ubiquitin level can reduce the activation threshold of cells to environmental stressors, and UBC has been thus proposed as one promising candidate biomarker together with calmodulin-like protein 5 for the identification of newborns predisposed to develop atopic eczema." (PMID 26793622, 2015).
endometrial cancer (2 papers, 2020 to 2022). Primary or metastatic malignant neoplasm involving the endometrium (mucous membrane that lines the endometrial cavity). "Melatonin inhibits endometrial cancer progression by inhibiting succinate accumulation induced by the estrogen/UBC/SDHB signaling pathway." (PMID 35263200, 2022). "PSMC4, PUM1 and IPO8 were identified as the best reference genes combination for type 1 endometrial cancer (grades 1, 2 and 3), whereas for type 2 endometrial cancer (serous and carcinosarcoma), UBC, MRPL19, PGK1 and PPIA were the best reference genes combination." (PMID 32439920, 2020).
endometriosis (2 papers, 2021). The growth of functional endometrial tissue in anatomic sites outside the uterine body. "The Ubiquitin C-GFP (UbC-GFP) model has also been used to study hematopoietic cells by allowing in vivo leukocyte tracking and hematopoietic cell differentiation in a murine model of endometriosis." (PMID 35095566, 2021). "Interestingly, we found the five most stable genes (EIF2B1, POP4, UBC, CASC3, and MRPL19) were not previously measured in endometriosis expression studies." (PMID 33686153, 2021).
gastric cancer (2 papers, 2020 to 2022). A primary or metastatic malignant neoplasm involving the stomach. "Simultaneous knockdown of UBB and UBC mRNAs induces gastric cancer cell apoptosis, resulting in decreased cell viability, thereby inhibiting gastric cancer cell metastasis." (PMID 35263200, 2022). "Regarding HSF1, its activity is mainly induced in response to different stressful conditions such as heat shock, oxidative stress or proteotoxic stress: this may account for the lack of effect on UBC and UBB gene transcription in HSF1 silenced gastric cancer cells." (PMID 32751694, 2020). "The lack of effect on UBC and UBB gene transcription in HSF1-silenced gastric cancer cells may depend on the fact that HSF1 is a stress-activated TF, while for YY1 we evaluated different target genes in the siYY1-transfected cells and we found that they are differently affected by YY1 knockdown." (PMID 32751694, 2020).
male infertility (2 papers, 2020 to 2024). The inability of the male to effect fertilization of an ovum after a specified period of unprotected intercourse. "Furthermore, most of them were associated with ubiquitin C, indicating that it could play an important regulation role, resulting in a potential male infertility biomarker." (PMID 32708913, 2020). "Both inducible whole-body PDI-KO (UBC-Cre/Pdifl/fl) mice and premeiotic PDI-KO (Stra8-Cre/Pdifl/fl) mice experienced a significant decrease in germ cells, testicular atrophy, oligospermia, and complete male infertility." (PMID 38912589, 2024).
neuroblastoma (2 papers, 2009 to 2010). Neuroblastoma (NB) is the most common solid, extracranial childhood tumor. "In this study, SDHA, UBC and GAPDH housekeeping genes were used as endogenous controls based on previous data which showed these genes to be most stably expressed in human neuroblastoma cells." (PMID 19445671, 2009).
Pancreatic Carcinoma (2 papers, 2012 to 2017). "In addition to these two genes, Ubiquitin C (UBC) in head and neck cancer and Transferrin receptor (TFRC) and β-Glucuronidase (GUSB) in pancreatic cancer were identified to be stable as well." (PMID 28262749, 2017).
periodontitis (2 papers, 2015 to 2023). An acute or chronic inflammatory process that affects the tissues that surround and support the teeth. "On the basis of our findings, we propose the cumulative use of UBC, JUN, and MMP14, possibly in combination with oral pathogenic bacteria-derived proteins, as putative biomarkers for early detection of periodontitis to be tested either at the RNA or protein level in salivary samples." (PMID 26793622, 2015). "We conclude that UBC, JUN, and MMP14 are likely an optimal candidate group of host-derived biomarkers, in combination with oral pathogenic bacteria-derived proteins, for detecting periodontitis at its early phase by using salivary samples from patients." (PMID 26793622, 2015).
alopecia (1 paper, 2018). Hair loss usually from the scalp. "However, despite apparently normal embryonic development and birthrates, the UBC-cre/ERT2;FLExDUX4 pups (stage P10) showed delayed fur growth compared with FLExDUX4/+ siblings, which further manifested as a mild alopecia by 3 weeks of age." (PMID 29415061, 2018).
Angelman syndrome (1 paper, 2017). A neurogenetic disorder characterized by severe intellectual deficit and distinct facial dysmorphic features. "Our String analysis puts the ubiquitin system (UBC) in a central point for ADNP regulatory pathways, and in that respect, Angelman syndrome is caused by ubiquitin protein ligase E3A mutations." (PMID 28221363, 2017).
asthma (1 paper, 2022). "Similarly, the UBC and MAPK1 genes have been linked with asthma, which is a common comorbidity of AR." (PMID 34637606, 2022).
atherosclerosis (1 paper, 2014). A disease characterized by the build-up of fatty material and calcium deposition in the arterial wall resulting in partial or complete occlusion of the arterial lumen. "Interestingly UBC controls the modulation of cell surface receptors and ion channels, and there is emerging evidence for its importance in the initiation of atherosclerosis and the proliferation of cardiovascular disease." (PMID 25519358, 2014).
bladder cancer (1 paper, 2020). "As they consistently ranked in the top ten by CoV, GeNorm and Normfinder, UBC, RPLP0, HMBS, GUSB, and TBP are the most suitable endogenous control genes for bladder cancer qPCR." (PMID 33057113, 2020).
breast tumor (1 paper, 2022). "Once a primary breast tumor was detected by palpation in experimental MMTV-PyMT; HK2f/f; UBC-CreERT2 mice and control MMTV-PyMT;HK2f/f mice, the mice were injected with tamoxifen for 7 consecutive days to systemically delete HK2 in the experimental MMTV-PyMT;HK2f/f;UBC-CreERT2 mice." (PMID 35173161, 2022).
bronchiolitis obliterans (1 paper, 2025). "The present findings highlight the pivotal role of ubiquitin dysregulation in the early stages of airway fibrosis and provide a molecular foundation for exploring UbC-targeted interventions in the prevention and treatment of bronchiolitis obliterans." (PMID 41394137, 2025).
chronic rhinosinusitis (1 paper, 2016). Chronic form of sinusitis. "And RPL-13A and ubiquitin C (UBC) were shown to be the most stable reference genes in a variety of human cells and tissues, while YWHAZ and HPRT1 were the most stable reference genes in partial degradation samples from chronic rhinosinusitis." (PMID 27069927, 2016).
cyst (1 paper, 2019). A sac-like closed membranous structure that may be empty or contain fluid or amorphous material. "Analysis of the cyst wall preparation also found TGME49_263300 (a putative homolog of TOM40), TGME49_219820 (a putative homolog of polyubiquitin C), and TGME49_221620 (a cytoskeletal protein tubulin)." (PMID 31040239, 2019).
cystic fibrosis (1 paper, 2017). Autosomal recessive disorder caused by pathogenic variants in the CFTR gene (cystic fibrosis transmembrane conductance regulator), which encodes a chloride and bicarbonate channel expressed in epithelial cells, and follow the diagnosis criteria. "Associated pathways indicate that immune system is likely involved and that Ubiquitin C is probably a central node, linking Cystic Fibrosis to liver and pancreatic disease." (PMID 28339466, 2017).
Duchenne muscular dystrophy (1 paper, 2021). Duchenne muscular dystrophy (DMD) is a neuromuscular disease characterized by rapidly progressive muscle weakness and wasting due to degeneration of skeletal, smooth and cardiac muscle. "In this study we have identified reference genes suitable for use in brain tissue from two important animal models of Duchenne muscular dystrophy, the DE50-MD dog and themdx mouse.SDHA, UBC andYWHAZ had stable expression in canine brain, andGAPDH, RPL13A andCYC1 in murine brain." (PMID 37942409, 2021).
gastric adenocarcinoma (1 paper, 2020). "Our preliminary evidence shows that combined targeting of poly-Ub genes UBB and UBC significantly affects the cellular Ub protein content in the two GC cell lines, being more detrimental for the viability of primary gastric adenocarcinoma 23132/87 cells." (PMID 32751694, 2020). "Our results identify UBB and UBC as pro-survival genes in primary gastric adenocarcinoma 23132/87 cells." (PMID 32751694, 2020). "Further in vitro experiments (i.e., using other GC cell lines such as AGS and SNU-16) and in vivo studies are needed to warrant UBB and UBC as potential therapeutic targets and Ub protein levels as a new biomarker in gastric adenocarcinoma." (PMID 32751694, 2020).
head and neck cancer (1 paper, 2017). A primary or metastatic malignant neoplasm affecting the head and neck. "Data analysis and ranking of the top 5 HKGs using geNorm and Normfinder identified UBC, TBP, IPO8, TFRC, GAPDH in head and neck cancer; TBP, IPO8, GUSB, UBC in lung and TBP, IPO8, TFRC, GUSB, HMBS in pancreas to be stable." (PMID 28262749, 2017).
Infertility (1 paper, 2015). "Overexpression of dimer hCG driven by either the ubiquitin C or MT promoter resulted in similar male phenotypes of infertility and Leydig cell hyperplasia with high testosterone levels." (PMID 26483755, 2015). "Similar to the ubiquitin C promoter-hCG mice, the progressive infertility in the KiLHRD582G mice was not due to sperm defects." (PMID 26483755, 2015). "The infertility in the ubiquitin C promoter-driven hCG mice was not due to defects in sperm but possibly due to the urethral obstruction." (PMID 26483755, 2015).
influenza (1 paper, 2025). An acute viral infection of the respiratory tract, occurring in isolated cases, in epidemics, or in pandemics; it is caused by serologically different strains of viruses (influenzaviruses) designated A, B, and C, has a 3-day incubation period, and usually lasts for 3 to 10 days. "The analysis revealed that the core targets of Chicoric acid against influenza are UBA52, UBC, HCK, CDKN1B, and RPS27A." (PMID 41303371, 2025).
Inguinal hernia (1 paper, 2020). Protrusion of the contents of the abdominal cavity through the inguinal canal. "We discovered that PIK3R1, PTPN11, TGFBR1, CDC42, SOS1, and KRAS were the most essential inguinal hernia-causative proteins and UBC, GRB2, CTNNB1, HSP90AA1, CBL, PLCG1, and CRK were listed as the most commonly-involved downstream proteins." (PMID 31910207, 2020). "Five essential proteins (PIK3R1, PTPN11, TGFBR1, CDC42, and SOS1) and three downstream common proteins (UBC, GRB2, and CTNNB1) were found to be related to inguinal hernia development." (PMID 31910207, 2020). "Most importantly, UBC, GRB2, and CTNNB1 were significantly enriched in the inguinal hernia PPI network." (PMID 31910207, 2020). "Thus, proteins PIK3R1, CDC42, TGFBR1, PTPN11, UBC, CTFR, and SOS1 may play an important role in the inguinal hernia PPI network." (PMID 31910207, 2020).
Insulin resistance (1 paper, 2019). Increased resistance towards insulin, that is, diminished effectiveness of insulin in reducing blood glucose levels. "Furthermore, UBC-SKO mice were glucose intolerant and had significantly higher concentrations of serum glucose as well as insulin 12 weeks after tamoxifen treatment, consistent with insulin resistance." (PMID 31404087, 2019).
keratitis (1 paper, 2010). A corneal disease that is characterized by inflammation of the cornea. "Namely, geNorm proposed PPIA and HRPT1 and PPIA and RPL5 pairs for chemical burn-induced CorNV in Balb/c and C57BL/6 mice, respectively, while UBC and HPRT1 and UBC and LDHA were best for Candida and Aspergillus induced keratitis in Balb/c mice, respectively." (PMID 20596249, 2010).
liver fibrosis (1 paper, 2025). "Wild-type (WT) and conditional UBC-Cre; Men1f/f (Men1Δ/Δ) allele homozygous knockout (KO) mice were treated with CCL4 to establish liver fibrosis models." (PMID 40651612, 2025).
lymphoma (1 paper, 2022). A malignant (clonal) proliferation of B- lymphocytes or T- lymphocytes which involves the lymph nodes, bone marrow and/or extranodal sites. "The HPA database results showed that the protein levels of TSR1, WDR46, HSP90AA1, and NOP56 in lymphoma were higher than those in normal lymphoid tissue, whereas the protein level of UBC in lymphoma was lower than that in normal lymphoid tissue." (PMID 35263200, 2022).